MUC1 (mucin 1, cell surface associated)
Diseases named in the same sentence as MUC1 in open-access papers (continued):
Sharing a sentence is not in itself a finding about the gene and the disease.
pancreatic cancer (continued). "A recent paper highlights the importance of proper model systems for studying the role of MUC1: in vitro, deletion of either the TR or the CT resulted in decreased invasion of transfected pancreatic cancer cells as compared to cells expressing full-length MUC1." (PMID 21655373, 2008). "Overexpression of MUC1 mucin in pancreatic tumours has been correlated with poor patient survival." (PMID 17912239, 2007). "Similarly, circulating anti-MUC1-IgG antibody levels were found predictive of survival in breast and pancreatic cancer patients." (PMID 17064405, 2006). "Overexpression of MUC1 was found in all three cell lines, suggesting that this overexpression may involve pancreatic cancer metastases and that cancer clones that escape from primary tumours do not lose the MUC1 antigen." (PMID 15599383, 2004). "The specific cytotoxic effects obtained in this in vitro study suggest this AIC may target and kill the majority of human primary and metastatic pancreatic cancer cells harbouring moderate to strong MUC1 overexpression." (PMID 15599383, 2004). "213Bi-C595 may be a useful agent for the treatment of micrometastases or minimal residual disease (MRD) in pancreatic cancer patients with overexpression of MUC1 antigen." (PMID 15599383, 2004). "MUC1 may provide a good basis for targeting pancreatic cancer cells in transit or in preangiogenic cancer cell clusters." (PMID 15599383, 2004). "We suggest that 213Bi-C595 may have the potential to target micrometastatic pancreatic cancer cells with MUC1 overexpression and represent a new therapeutic modality for the control of pancreatic cancer metastases." (PMID 15599383, 2004). "MUC1, a transmembrane glycoprotein, is minimally expressed and heavily glycosylated in normal tissues but aberrantly overexpressed and hypoglycosylated in epithelial tumors such as pancreatic cancer, exposing tumor-specific epitopes and making it an ideal target for immunotherapy." (PMID 41607777, 2026). "MUC1 may also regulate metabolism in pancreatic cancer cells interacting with HIF-1α." (PMID 40001578, 2025). "In addition, MUC1 is also an overexpressed target in pancreatic cancer." (PMID 38833359, 2024). "Additionally, MUC1 suppression makes pancreatic cancer cell lines more sensitive to 5-FU." (PMID 36831413, 2023). "Furthermore, 5E5, one of the anti-Tn mAb that specifically recognizes Tn-carrying MUC1 (Tn+MUC1), was employed on chimeric antigen receptor T-cell (CART), and demonstrated specific cytotoxicity to leukemic and pancreatic cancers with Tn+MUC1 expression using an in vivo xenografted mouse model." (PMID 37509200, 2023). "Consequently, the regulatory axis of MUC1-P13k signaling might be suggested as a potent therapeutic target in pancreatic cancer." (PMID 35686109, 2022). "Taken together, our study provides a new immunotherapy strategy for improving the cross-presentation ability of therapeutic vaccine, which may be applicable to pancreatic cancer, lung cancer and for targeting other types of solid tumors that highly express MUC1 and PD-L1." (PMID 35891256, 2022). "Furthermore, MUC1 inhibition also sensitizes pancreatic cancer cell lines to 5-FU." (PMID 32122374, 2020). "Nevertheless, since the AS1411 aptamer has been shown to potently bind to PDAC cells in other studies, and since MUC1 is expressed in PDAC cells as well, metal (nano) formulations of both the AS1411- and the anti-MUC1- aptamer could potentially be used as radiosensitizers for pancreatic cancer." (PMID 32758252, 2020). "A previous work has shown that high numbers of MUC-1pos/EpCAMpos CTCs correlate with shorter overall survival in patients with pancreatic cancer, and data suggest that MUC-1 and EpCAM might identify different subtypes of CTCs in pancreatic, but also in ovarian and metastatic breast cancer." (PMID 32290064, 2020).
pancreatic cancer (continued). "Similarly, over 15% of pancreatic cancers develop from premalignant cysts in the pancreas known as intraductal papillary mucinous neoplasm (IPMN) that are lined by multiple layers of proliferative ductal epithelial cells overexpressing tumor forms of MUC1." (PMID 31275327, 2019). "Western blot confirmed stable MUC1 expression in multiple pancreatic cancer cell lines (PANC-1, BxPC-3, MIA PaCa-2), providing a molecular rationale for MUC1-targeted immunotherapy." (PMID 41607777, 2026). "MUC1 peptide-pulsed DCs effectively activate specific CTL responses, indicating that DC-based vaccine immunotherapy holds promise for the management of pancreatic cancer." (PMID 41607777, 2026). "Beyond mesothelin, additional targets such as prostate stem cell antigen (PSCA), carcinoembryonic antigen (CEA), mucin-1 (MUC1), and CD24 have shown efficacy in preclinical models of pancreatic cancer." (PMID 40940995, 2025). "Next, using a standard 5-hr 51Cr-release assay, we evaluated the cytolytic activity of these CAR-modified cells against CAPAN1 pancreatic cancer cells, which express both target TAAs, albeit at different levels (PSCA – 95.1% and MUC1 – 68.5%)." (PMID 40808942, 2025). "Crosstalk between MUC1 and HIF-1α signaling renders pancreatic cancer resistant to gemcitabine by inducing anabolic glucose metabolism." (PMID 39588377, 2024). "MUC1 is overexpressed in pancreatic, lung, breast, colon, and ovarian cancers, while MUC4 overexpression has been observed in colon adenocarcinoma and pancreatic cancer." (PMID 39767713, 2024). "emphasized that in pancreatic cancer precursor lesion intraductal papillary mucinous neoplasm (IPMN), abnormal expression of MUC1 promotes specific immune responses, including IgG production and T cell infiltration." (PMID 38361923, 2024). "The results revealed that Gal-3 influenced the cellular distribution of MUC1 and EGFR in pancreatic cancer cells." (PMID 37915694, 2023). "We unveil for the first time that pancreatic cancer cells (PANC-1) and secreted exosomes express MUC1 bearing cancer-relevant dynamic epitopes recognized specifically by an anti-MUC1 antibody (SN-131)." (PMID 37547453, 2023). "At a threshold of 96% specificity, 78% and 83% of pancreatic cancer patients showed increased expression of CA19-9 in MUC5AC and MUC1, respectively." (PMID 37455827, 2023). "The results clearly indicate that MUC1 TRD with multiple ST antigens is crucial for distinctively prolonged circulation and broad organ biodistribution of exosomes secreted from pancreatic cancer cells." (PMID 37547453, 2023). "Genes that were upregulated in low-MUC1 PDA samples (MAPK12, RASD1, and AMH) were found to be favorable for OS in pancreatic cancer (Human protein atlas)." (PMID 35237602, 2022). "Enolase 1 (ENO1), MUC1, survivin, and VEGFR-2-targeting DNA vaccines are examples of the DNA-based pancreatic cancer vaccines explored so far." (PMID 36224645, 2022). "It was also discovered that the fluorescence intensity of pancreatic cancer cells was significantly higher than that of HPDE-C7 and HepG-2 cells (control cell lines), which express lower MUC1 protein." (PMID 35197099, 2022). "When pancreatic cancer cells are present in the PBS buffer, the MUC1 Apt in the probe will bind to the MUC1 protein through the specific recognition, and release the Tri for starting the HCR amplification." (PMID 35197099, 2022). "This study analyzed the relationship between the expression level of the mucin family and its subtypes (MUC1, MUC4, MUC5, MUC16) and the overall survival of patients with pancreatic cancer." (PMID 35709153, 2022). "Krebs von Lungen 6, which is a subtype of mucin 1 (MUC1), has been mostly investigated in biliary or pancreatic cancers." (PMID 35328248, 2022). "In short, the strategy using MUC1 probe, HCR amplification and Fe3O4@DOP NPs shows the potential applications for pancreatic cancer detections." (PMID 35197099, 2022).
pancreatic cancer (continued). "As an IgG1 mouse antibody, DS6 can recognize MUC1’s CA6 sialoglycotope which shows overexpression in various solid tumor types, such as BRCA, ovarian cancer (OC), lung cancer (LC), pancreatic cancer, and cervical cancer (CC)." (PMID 35883508, 2022). "The MUC1 cDNA-transfected human autologous DC vaccines were adopted to treat ten advanced BRCA, papillary, or pancreatic cancer cases." (PMID 35883508, 2022). "Mucin 1 (MUC1), a transmembrane mucin glycoprotein, regulates PDGFA expression and secretion in pancreatic cancer cells, accordingly, influences the proliferation of pancreatic tumors." (PMID 34858977, 2021). "MUC1 also contributes to altering the pentose phosphate pathway (PPP) and the nucleotide metabolism of pancreatic cancer cells." (PMID 34681277, 2021). "The PDACEV signature calculated as the unweighted sum of EGFR, EPCAM, MUC1, GPC1, and WNT2 signals showed an 86% sensitivity and 81% specificity in distinguishing pancreatic cancer patients from healthy controls." (PMID 33803470, 2021). "MUC1-MAG signaling pathway contributes to the increased invasiveness and proliferation of pancreatic cancer cells." (PMID 33718210, 2021). "They showed that hypomethylation of MUC1 and MUC4 promoters correlates with mRNA and IHC positivity of both mucins in pancreatic cancer tissues, and with a high CA9 level." (PMID 32707920, 2020). "Here we show interlukine-17 receptor B (IL-17RB) expression is positively correlated with MUC1 and MUC4 expression in pancreatic cancer cells and tumor tissue." (PMID 33082357, 2020). "To examine the roles of MUC1 and MUC4 in IL-17RB-mediated stemness in the pancreatic cancer cells, we overexpressed FLAG-tagged IL-17RB, followed by knockdown of MUC1 and MUC4 by lentivirus-based shRNA in SU.86.86 cells." (PMID 33082357, 2020). "Mucins, especially the highly-glycosylated MUC1, MUC4, MUC5AC, and MUC16, are prominently observed in pancreatic cancer and major carriers of glycans including the CA 19-9 antigen." (PMID 32582529, 2020). "The overexpression of oncogenes MUC1 and MUC13 have been well established in many solid tumors including pancreatic cancer." (PMID 33198082, 2020). "Together, these results indicate IL17B/IL-17RB signaling is potentially involved in transcriptional regulation of MUC1 and MUC4 expression in pancreatic cancer cells." (PMID 33082357, 2020). "The PAM4 mAb, which recognizes a carbohydrate-induced conformational epitope on MUC1 and MUC5AC, has been evaluated as a targeting vehicle for therapy and imaging of pancreatic cancer." (PMID 33371487, 2020). "To evaluate the correlation between IL-17RB, MUC1 and MUC4, we examined the expression of these genes in a panel of human pancreatic cancer cell lines." (PMID 33082357, 2020). "Apart from these, another MUC member, MUC1, which has a similar structure to MUC16, interacts with p120ctn to regulate the dynamic features of cell adhesion, motility and metastasis in pancreatic cancer." (PMID 30795761, 2019). "Mucins are known to be present in pancreatic cancer, with elevated expression of multiple MUC family including MUC1." (PMID 29987260, 2018). "Most experience with DC-based vaccination has been gathered for MUC1 and WT1 antigens, where clinical studies in advanced pancreatic cancer have provided encouraging results." (PMID 29946224, 2018). "The number of MUC1- and CA19-9-positive vesicles differed significantly between the two cancer types, with MUC1 expression higher in colorectal cancer and CA19-9 expression higher in pancreatic cancer." (PMID 28317069, 2017). "Connecting chemoresistance with Neu1 sialidase, another report found that MUC1 induces drug resistance in human (BxPC3 and Capan-1) and mouse (KCKO, KCM) pancreatic cancer cells." (PMID 27029067, 2016).
pancreatic cancer (continued). "Our results provide the first evidence that in concert with ERK activation, MUC1 modified the formation of AP-1 dimers to preferentially favor c-Jun:FRA-1, which in turn enhanced the migration and invasive potential of pancreatic cancer cells in vitro." (PMID 27220889, 2016). "We initially evaluated the possibility that this was due in part to the influence of MUC1 on levels of c-Jun in two MUC1 overexpressing human pancreatic tumor cell lines, S2013.MIF and Panc1.MUC1, as compared to their low-expressing counterparts." (PMID 27220889, 2016). "In this report, we found that MUC1 modulated AP-1 (c-Jun and FRA-1) activity and thereby affected the migratory and invasive properties of pancreatic cancer cells." (PMID 27220889, 2016). "In summary, we show that MUC1 enhancement of ERK activation influences FRA-1 activity to modulate tumor migration, invasion and metastasis in a subset of pancreatic cancer cases." (PMID 27220889, 2016). "MUC1 and MUC4 have been reported to play significant roles in pancreatic cancer growth, proliferation, metastasis and drug resistance." (PMID 26046375, 2015). "Among the several members of the mucin family, expression of MUC1, MUC4, and MUC5AC were found to be significantly elevated in the malignant stage of pancreatic cancer." (PMID 26046375, 2015). "To create a more effective therapy for pancreatic cancer, we conducted combined AIT with MUC1-CTLs and MUC1-mRNA–transfected dendritic cells (MUC1-DCs) plus GEM." (PMID 24947606, 2014). "Since MUC1, MUC2 and MUC4 are key mucins in pathological diagnosis of pancreatic neoplasms, our goal is to apply DNA methylation analysis of the three mucin genes using pancreatic juice for early diagnosis of these neoplasms." (PMID 24714692, 2014). "MUC1-CTLs were induced by co-culture with YPK-1, a human pancreatic cancer cell line, and then with interleukin-2." (PMID 24947606, 2014). "PAM4, a monoclonal antibody to MUC1, is an lgG1 immunoglobulin produced by immunization of mice with mucin purified from the xenografted RIPI human pancreatic cancer—originally a mucinous, moderately differentiated tumor in the head of the pancreas." (PMID 24818166, 2014). "MSE showed that gastric-type IPMNs have a significantly lower U-index for MUC1 than other pancreatic neoplasms, indicating that MSE of MUC1 is useful to identify gastric-type IPMNs." (PMID 24714692, 2014). "Since the pancreatic cancer cells used in this study have high, albeit heterogeneous, MUC16 expression, in addition to heterogeneous MUC1 expression, we wanted to investigate the immune shielding effect of MUC1 and MUC16 in regard to ADCC." (PMID 24039759, 2013). "In pancreatic cancer, several trials have shown that use of a TAA such as MUC-1 in combination with CEA or K-Ras can elicit an immunologic response and possibly improve outcomes in those mounting such a response." (PMID 24829746, 2013). "Since MUC1 protein is overexpressed on the surface of multiple types of cancer cells, such a drug delivery system may potentially improve the delivery of anticancer agents to multiple malignancies, such as pancreatic cancer, prostate cancer, ovarian cancer, etc." (PMID 21912664, 2011). "The apomucins MUC1, MUC5B, MUC5AC, and MUC6 are expressed in the normal pancreas; MUC1, MUC2, and MUC4 are upregulated in pancreatic tumours, whereas MUC5B, MUC5AC, and MUC6 are slightly downregulated." (PMID 14760381, 2004). "Information regarding the role of MUC1 and MUC4 in the growth of primary pancreatic tumours has remained scarce until recently." (PMID 15494719, 2004). "Breast and pancreatic cancer patients may spontaneously develop a specific, MHC-independent cytotoxic T-cell response against epitopes in the protein core of tumour-associated MUC1; however, MHC class I and class II restricted cellular immune reactions against MUC1 protein were observed as well." (PMID 12966437, 2003).
pancreatic cancer (continued). "The peptide-pulsed DC vaccines significantly increased the proportion of CD8+ T cells among CTLs and mediated dose-dependent cytotoxic effects against pancreatic cancer cell lines (PANC-1, BXPC-3, MIA PaCa-2), with the highest efficacy observed in the MUC1 peptide 619 group." (PMID 41607777, 2026). "In a study of mostly pretreated patients with unresectable advanced pancreatic cancer, participants received a WT-1 peptide-pulsed DC vaccine with or without other peptides, including MUC-1, CEA, or CA-125." (PMID 40723238, 2025). "Furthermore, knockout of MUC1 in tumor cells resulted in higher sensitivity to EGFR inhibitors, and activated EGFR stimulated MUC1 expression in human uterine and pancreatic cancer cell lines." (PMID 39664199, 2024). "highlighted the role of MUC1 and MUC16 in breast and pancreatic cancer cells, showing that reducing their expression through COSMC gene knockdown enhances tumor cell sensitivity to natural killer cell-mediated antibody-dependent cellular cytotoxicity (ADCC) and cytotoxic T lymphocyte (CTL) killing." (PMID 38361923, 2024). "Additionally, the role of MUC1 and MUC16 in pancreatic cancer progression has been extensively validated." (PMID 38361923, 2024). "A canonical function of TARS1 has been suggested in pancreatic cancer, where the overexpression of Mucin1 (MUC1) and cell migration are dependent on high levels of TARS1 due to an unusually high number of threonine residues in the amino acid sequence of MUC1." (PMID 38477373, 2024). "Moreover, MUC1 is a prognostic marker for colorectal adenocarcinoma, while MUC4, MUC1 and MUC5A are reported as biomarkers for pancreatic cancer." (PMID 35454762, 2022). "MUC1 positive (Capan-2, CFPAC-1, PANC-1), MUC1 negative pancreatic cancer lines and Normal pancreatic duct cell line hTERT-HPNE were treated with different concentrations of human IgG-MMAE, HzMUC1-MMAE and analyzed using colony formation assay." (PMID 36572921, 2022). "In pancreatic cancer cell lines, miR-29a and miR-330-5p can inhibit cell proliferation, migration, and invasion and sensitize pancreatic cancer cells to gemcitabine by directly binding to the 3′ UTR of MUC1 to suppress its expression." (PMID 35154471, 2022). "Therefore, we emphasize here that the HzMUC1 antibody recognizes a MUC1 isoform, which contains SEA domain, expressed on the surface of pancreatic cancer cells." (PMID 36572921, 2022). "The involvement of KL-6/MUC1 glycosylation in the metastasis of and invasion by pancreatic cancer cells has also been shown and may be related to the EMT process." (PMID 34207342, 2021). "On the other hand, MUC1 directly exploits the drug efflux system through the transcription of multidrug resistance (MDR) genes, which has been reported to protect both lung and pancreatic cancer cells from chemotherapeutics." (PMID 34681277, 2021). "Moreover, Mucin glycoproteins, among them Mucin 1 (MUC1), are highly expressed in pancreatic cancer and detectable with monoclonal antibodies, such as PAM4 (clivatuzumab), that are reactive to MUC1." (PMID 33147766, 2020). "IL-17RB, MUC1, and MUC4 are mainly expressed on the surface membrane of pancreatic cancer cells." (PMID 33082357, 2020). "Collectively, these results suggest IL-17RB could enhance gemcitabine resistance through upregulation of MUC1 and MUC4 in pancreatic cancer cells." (PMID 33082357, 2020). "Furthermore, it was observed that MUC1 and MUC4 are involved in IL-17RB-mediated resistance to gemcitabine in pancreatic cancer cells." (PMID 33082357, 2020). "99mTc labeled anti-KL-6/MUC1 antibody was shown to be a tumor-specific radiotracer that detects pancreatic cancer in vivo, but no further information is available." (PMID 33167508, 2020). "Moreover, sLex, also called CD15s, is overexpressed on liver acute-phase proteins, including haptoglobin and ceruloplasmin and on mucins MUC1, MUC5AC, and MUC6 in pancreatic cancer." (PMID 33371487, 2020).